CD79A (CD79a molecule)
Diseases named in the same sentence as CD79A in open-access papers (continued):
Sharing a sentence is not in itself a finding about the gene and the disease.
diffuse large B-cell lymphoma (25 papers, 2006 to 2025). "This signaling pathway is subverted in diffuse large B-cell lymphoma (DLBCL) and other B-cell malignancies by mutations of key signaling molecules, including CD79A/B and CARD11." (PMID 29690649, 2018). "Due to the abnormal expression of certain B-cell antigens (such as PAX-5+, CD79a+) by the tumor cells, the initial pathological report incorrectly diagnosed the lesion as “diffuse large B-cell lymphoma”." (PMID 41561755, 2025). "Certain oncogenic changes in the immunotyrosine-based activation motif (ITAM) of CD79a and CD79b have been reported to occur in diffuse large B-cell lymphoma (DLBCL), which drive the segregation of the activated B-cell-like subtype." (PMID 39770542, 2024). "Notably, similar deletions in the 4th and 5th exon of CD79A have been observed in diffuse large B-cell lymphoma, which has been shown to impact the ITAM signaling modules." (PMID 38769532, 2024). "Initial histopathological examination of the resected lesion, due to aberrant expression of B-cell markers (PAX-5, CD79a, c-Myc, Bcl-2), led to a misdiagnosis of diffuse large B-cell lymphoma (DLBCL)." (PMID 41561755, 2025). "Diffuse large B‐cell lymphoma is the most common type of testicular lymphoma, typically expressing CD19, CD20, CD22, CD79a, and PAX5 markers." (PMID 40735721, 2025). "Diffuse large B‐cell lymphoma typically expresses pan‐B markers CD19, CD20, CD22, CD79a, CD45RA, PAX5 markers, and other markers CD10, BCL6, BCL2, MYC, and MUM‐1." (PMID 40735721, 2025). "Research indicates that in cases of CD20-negative diffuse large B-cell lymphoma (DLBCL), the inclusion of CD79a and PAX5 in the immunohistochemical panel can significantly enhance diagnostic specificity and sensitivity." (PMID 40428800, 2025). "A 52-year-old woman was diagnosed with primary mediastinal of differentiation CD20 (+), CD79a (+), Bcl-2 (+), Bcl-6 (partial+), MUM1 (partial+) diffuse large B cell lymphoma (DLBCL) almost six months prior." (PMID 38561816, 2024). "It is estimated that 90% of PCNSL is diffuse large B cell lymphoma (DLBCL), which expresses universal B cell markers (CD19, CD20, CD79a)." (PMID 36596785, 2023). "Concerning the pathological subtype, the vast majority of PCNSLs (>95%) are diffuse large B-cell lymphomas (DLBCLs), expressing B-cell markers such as CD20, CD19, CD79a, and immunoglobulin light chains." (PMID 34485125, 2021). "A vast majority of PCNSL cases are comprised of a diffuse large B cell lymphoma (DLBCL) and express pan-B cell markers CD20, CD19, CD22, and CD79a." (PMID 34771535, 2021). "Two new MoAbs approved for treatment of relapsed or refractory diffuse large B cell lymphoma (DLBCL) are the anti-CD19 tafasitamab, and the anti-CD79a conjugated with monomethyl auristatin E polatuzumab vedotin." (PMID 33322351, 2020). "Histological examination of the biopsy specimens confirmed the diagnosis of diffuse large B-cell lymphoma (DLBCL); immunochemical staining was positive for CD20 and CD79a." (PMID 29546569, 2018). "Positive staining for p63 initially raised suspicion for poorly differentiated urothelial carcinoma; however, lack of staining for pancytokeratin and positive staining for LCA, CD20, CD79a, and PAX-5 confirmed the diagnosis of diffuse large B cell lymphoma." (PMID 27648316, 2016). "Diffuse large B-cell lymphoma was most commonly positive for CD20 and CD79a and less commonly positive for germinal centre cell markers CD10 and BCL6." (PMID 19116013, 2008). "In contrast to HS, diffuse large B-cell lymphoma constantly express various pan-B markers such as CD19, CD20, CD22, and CD79a, while anaplastic large cell lymphomas are positive for CD30, and ALK." (PMID 17324277, 2007). "Postoperative pathology revealed diffuse large B-cell lymphoma (DLBCL), with immunohistochemically related positive indicators, including CD20, CD79a, LCA, MUM-1, PAX5, C-MYC, BCL-2, and BCL-6, in all patients." (PMID 35734472, 2022).
diffuse large B-cell lymphoma (continued). "Some cases of diffuse large cell B-lymphoma CD30+ of an anaplastic variant may represent a diagnostic challenge, especially if CD20 and CD79a are negative." (PMID 32013101, 2020). "Biopsy and pathology analysis revealed a diffuse large B-cell lymphoma (DLBCL), with positive staining for CD20, CD79a, BCL2 and BLC6, but negative for CD10; 30% of the cells were positive for MIB-1 but MUM1 (IRF4) staining was negative, suggesting a germinal center-type lymphoma." (PMID 39110273, 2024).
colon carcinoma (22 papers, 2014 to 2025). "A risk score system consisting of eight immune-related genes (IRGs) (FGFR2, ZC3HAV1L, TNFRSF11B, CD79A, IGHV3-11, IGHV3-21, IGKV2D-30, and IGKV6D-21) was constructed to predict the prognosis of colon cancer patients." (PMID 34938284, 2021). "A risk scoring system consisting of eight IRGs (FGFR2, ZC3HAV1L, TNFRSF11B, CD79A, IGHV3-11, IGHV3-21, IGKV2D-30, and IGKV6D-21) was constructed to evaluate the prognosis of colon cancer patients based on multivariate Cox analysis." (PMID 34938284, 2021).
ovarian carcinoma (21 papers, 2011 to 2025). A malignant neoplasm originating from the surface ovarian epithelium. "The results suggest that both peripheral blood markers and TICs can be used as prognostic predictors in patients with ovarian cancer, and CXCL9, CD79A, MS4A1, and MZB1 may be potential therapeutic targets for ovarian cancer immunotherapy." (PMID 36645174, 2023).
hepatocellular carcinoma (19 papers, 1975 to 2025). A malignant tumor that arises from hepatocytes. "Key markers, such as PTPRC, CD3E, CD4, CD79A, and CD3G in immune cells, EPCAM and KRT19 in epithelial cells, and MME and PECAM1 in stromal cells, were identified, providing crucial insights into hepatocellular carcinoma progression and immune response mechanisms." (PMID 39388011, 2024).
MALT lymphoma (19 papers, 2013 to 2025). An indolent, extranodal type of non-Hodgkin lymphoma composed of small B-lymphocytes (centrocyte-like cells). "MALT tumor cells express B-cell-associated antigens, such as CD20 and CD79a, which are positive in MALT lymphomas." (PMID 38640287, 2024). "The biopsy specimen demonstrated the dominance of lymphoid cells and tested positive for CD20, CD79a, Bcl-2, and IRTA-1, which is consistent with the findings in MALT lymphoma." (PMID 38694936, 2024). "In immunohistochemistry, MALT lymphoma cells are CD20+, CD79a+, BCL2+, BCL6−, CD5−, CD10−, and CD23−." (PMID 35053607, 2022). "MALT lymphoma cells immunohistochemically exhibit CD20+, CD79a+, CD5-, CD10-, CD23-, CD43+/-, and cyclin D1-." (PMID 36614921, 2022). "Immunophenotypically, MALT lymphoma cells are CD20+, CD79a+, BCL2+, and IgM+." (PMID 40831827, 2025). "MALT lymphomas express B-cell-associated antigens (CD20, CD22, and CD79a) and are negative for CD5, CD10, and CD3." (PMID 23476858, 2013). "The IHC profile of plasmablastic lymphoma is relatively similar to that of other plasma cell neoplasms, large B-cell lymphomas, and MALT lymphoma, in which CD30, CD38, CD138, and CD79a are positive; however, CD20 is often negative." (PMID 37046526, 2023). "MALTomas that showed plasmacytic differentiation of lymphoid cells were excluded using IHC markers where MALT lymphomas were CD20+, CD79a + and SPs were typically CD20 negative." (PMID 31412808, 2019).
leukemia (16 papers, 2013 to 2025). A malignant (clonal) hematologic disorder, involving hematopoietic stem cells and characterized by the presence of primitive or atypical myeloid or lymphoid cells in the bone marrow and the blood. "Immunopositivity for CD45, CD43, and CD79a are useful for separating lymphoblastic lymphoma/leukemia from PNET." (PMID 25475214, 2014). "Being expressed in all stages of B-cell development and having a significant value on the European Group for the Immunological Characterization of Acute Leukemias scoring system, CD79a is considered as an excellent pan-marker for lineage assignment of B cells by flow cytometry." (PMID 34706776, 2021). "Furthermore, we show that downregulation of CD79a hampers the engraftment of leukemia cells in different murine xenograft models, particularly in the CNS." (PMID 33452446, 2021). "However, CD79a has also been found in some cases of myeloid leukemia, termed biphenotypic leukemia, in which CD79a was coexpressed with myeloid markers on bone marrow blast cells." (PMID 24146823, 2013). "Currently it is not clear whether the expression of CD79a in these biphenotypic leukemias is just a marker of aberrant lineage commitment and differentiation in tumor cells, or whether it plays a functional role independent of the BCR." (PMID 24146823, 2013). "As expected, leukemias expressed T-cell specific markers (Lck, CD4, CD8, and TCRα and β), but not B-cell specific genes (e.g. Pax5, CD79a or IgM), indicating they were of T-cell origin." (PMID 35581375, 2022).
plasmacytoma (16 papers, 2009 to 2026). Plasmacytoma is a localized mass of neoplastic monoclonal plasma cells that represents approximately 5% of all plasma cell neoplasms. "However, it typically expresses EBV, demonstrated by EBER-ISH positivity, and may retain B-cell markers like CD20 or CD79a, which are usually absent or only weakly expressed in plasmacytomas." (PMID 40821286, 2025). "The tumor cells were lambda light chain restricted and positive for CD45, weakly positive for CD79a and negative for CD20, CD30, CD10, CD5, BCl-2, Bcl-6, Pax5 and S100, and consistent with anaplastic plasmacytoma." (PMID 19495405, 2009).
pulmonary TB (16 papers, 2007 to 2025). "Their single-cell RNAseq analysis indicated the relative number of CD79A+ B cells was higher in the pulmonary TB compared with latent TB infection." (PMID 38899881, 2024).
Atrophy (15 papers, 2015 to 2026). Any weakening or degeneration, especially through lack of use. "However, in a case described by Nanri with cerebellar atrophy, Purkinje cell loss and mild Bergmann gliosis, no lymphocytic infiltration was observed (CD3-, CD4-, CD8-, CD20-, CD68-, CD79A-)." (PMID 32244870, 2020).
Granuloma (15 papers, 2008 to 2025). A compact, organized collection of mature mononuclear phagocytes, which may be but is not necessarily accompanied by accessory features such as necrosis. "However, directly surrounding the granulomas, B cells were numerous as visualized with CD20 or CD79a stainings." (PMID 27468085, 2016).
chronic lymphocytic leukemia (14 papers, 2012 to 2026). "One was B small lymphoid cell lymphoma/chronic lymphocytic leukemia: the expression rates of CD5, CD23, CD20, and CD79a were 100%, and the Ki67 index was ≥40%." (PMID 35242496, 2022). "Immunohistochemically, small lymphocytic lymphoma expresses IgM/IgD, CD20, CD22, CD5, CD19, CD79a, CD23, CD43 and CD11c." (PMID 22333190, 2012). "Additionally, cells classically stain positive for the B‐cell associated antigens CD20 and CD79a, with negative staining for CD5, CD10, and CyclinD1 to rule out small lymphocytic lymphoma, follicular lymphoma, and mantle cell lymphoma, respectively." (PMID 40236309, 2025).
T-cell lymphoma (14 papers, 2009 to 2025). "At immunohistochemistry, the prevalent cell immunoreactivity for B cell markers (CD20, CD79a, and PAX5) or for the T cell marker (CD3) was considered diagnostic for B cell (BCL) and T cell lymphoma (TCL), respectively." (PMID 36157173, 2022). "As ectopic Pax5 expression in the T‐lymphoid lineage leads to the development of an aggressive T cell lymphoma, we used the Cd79a‐Cre line to convert the Ikzf1neo to the Ikzf1Pax5 allele only at the onset of B cell development." (PMID 35156727, 2022). "Upon necropsy, a multicentric T-cell lymphoma (CD3+ CD79a−) of the thymus, kidney and lumbar lymph node was observed." (PMID 26689419, 2015). "However, similar to the current case report, only one case report described CD79a expression in a mature T-cell lymphoma." (PMID 24066244, 2013). "Approximately 10-15% of DLBCLs remain unclassifiable, and immunophenotyping and morphological analysis are critical to distinguish between B-cell and T-cell lymphomas, using markers such as CD3, CD5, CD20, and CD79a." (PMID 40959338, 2025). "In contrast, T-cell lymphoma (PTCL) shows expression of CD3 by lacking CD79a and CD20, characterizing them as T-cell type in IHC." (PMID 38828367, 2024). "Finally, the subtype T-zone lymphoma (TZL), is an indolent low-grade T-cell lymphoma, in which frequent CD25 and CD3 expression is accompanied by missing CD45, CD79a and CD20." (PMID 38828367, 2024). "In T-cell lymphomas, tumour cells showed cytoplasmic expression of CD3 and were negative to CD20 and CD79a." (PMID 40045318, 2025). "The addition of CD20, CD79a, CD3 and CD45RO to the antibody panel excludes B-cell and T-cell lymphomas." (PMID 36545668, 2022).
Hyperglycemia (12 papers, 2012 to 2025). An increased concentration of glucose in the blood. "Nine months later, pancreas allograft biopsy performed due to new-onset hyperglycemia (HgA1C 8.6%, C-peptide 6.15ng/mL and anti-GAD 0.9UI/mL) revealed a monotypic plasma cell infiltrate, CD19, CD79a, CD138 positive, with IgG-kappa light chain restriction, and EBV negative." (PMID 31236295, 2019).
liver cancer (12 papers, 2019 to 2025). An epithelial or non-epithelial malignant neoplasm that arises from the liver. "Interestingly, we found that most of these key node genes play important roles in tumorigenesis (RET, CEACAM5), immune regulation (CTSG, CD79A) and the EMT pathway (COL10A1, COL11A2), suggesting their significant role in the recurrence of liver cancer." (PMID 34956309, 2021).
Parkinson disease (12 papers, 2018 to 2024). A progressive degenerative disorder of the central nervous system characterized by loss of dopamine producing neurons in the substantia nigra and the presence of Lewy bodies in the substantia nigra and locus coeruleus. "Studies have confirmed that genes modulated during the pathogenesis of Parkinson’s disease appear in our regulatory network, and include CD79A and NLRP3 in addition to miRNAs associated with PD models, including miR-142-3p, miR-15b-5p, and miR-590-3p." (PMID 30665415, 2019).
Burkitt lymphoma (11 papers, 2014 to 2025). A rare form of malignant mature B-cell non-Hodgkin lymphoma. "It is also known that Burkitt lymphoma cells express surface immunoglobulin M and B cell-associated antigens (CD19, CD20, CD22, and CD79a)." (PMID 30233648, 2018). "B-cell markers, including CD22, CD19, CD79a, CD20, Pax5, and germinal center markers, such as CD10 and BCL-6, are expressed in Burkitt lymphoma." (PMID 40115528, 2025). "The immunohistochemistry results of laparoscopic biopsy revealed Burkitt lymphoma, characterized by positive expression of CD20, CD79a, CD10, BCL-6, MUM1, and strong positive expression of CD38, c-myc, cyclinD1, and Ki-67 positive index >90%+." (PMID 39993110, 2025). "Histochemical staining found positive leucocyte common antigen (LCA), positive CD20 and positive Bc-16 as well as positive CD79a and CD10 in cases of Burkitt lymphoma." (PMID 27182246, 2016). "Burkitt lymphoma has a germinal center B-cell (GCB) immunophenotype and is positive for the pan-B-cell antigens CD20, CD79a, and PAX5, and germinal center antigens CD10 and Bcl6." (PMID 26416427, 2015). "Immunohistochemical and molecular studies demonstrated typical features of sporadic Burkitt lymphoma: the atypical cells were positive for CD20, CD79a, CD10, CD23, HLA-DR, bcl-6, PAX5, c-myc, and cytoplasmic IgM, but negative for CD3, CD5, CD15, CD30, CD34, TdT, bcl-2, and MUM1." (PMID 34868769, 2021). "Then, to reach a final diagnosis of Burkitt’s lymphoma, immunohistochemical stainings should provide evidence that lymphomatous cells express CD19, CD20, CD10, and CD79a and no CD3, CD5, Bcl2, and TdT." (PMID 30453922, 2018).
candidiasis (11 papers, 2013 to 2024). Infection with the organism Candida. "As plasma cells containing IgG are also known to be in abundance in the lamina propria in oral candidosis, detection of CD79a and CD138 positive cells could offer improved understanding of the plasma cell infiltrate in these infections." (PMID 31718115, 2019).
Hodgkins lymphoma (11 papers, 1979 to 2026). A heterogeneous group of malignant lymphoid neoplasms of B-cell origin characterized histologically by the presence of Hodgkin and Reed-Sternberg (HRS) cells in the vast majority of cases. "CD79A is an important target of classical Hodgkin’s lymphoma; patients with high CD79A expression have a worse prognosis than those with low CD79A expression." (PMID 37344840, 2023). "Variable expression of CD20 and even less commonly CD79a in cases of Hodgkin's disease has also been demonstrated." (PMID 17949508, 2007). "CD79A was often used as the marker of the B-cell-relevant tumor, such as Hodgkin’s lymphoma." (PMID 36561317, 2022).
pancreatic cancer (11 papers, 2011 to 2026). "Instead, the miR expressing cells are located within clusters of CD79A positive cells, indicating that miR-125b-5p may play a role in B-lymphocyte/plasma cell infiltration in pancreatic cancer stroma." (PMID 34484811, 2019).
cyst (10 papers, 2008 to 2023). A sac-like closed membranous structure that may be empty or contain fluid or amorphous material. "Further study is necessary to examine the detailed analysis of B cell behaviors in the Cd79a-Tsc1 KO kidney and to trace the changes until the later stage of cyst formation." (PMID 36627370, 2023). "In Cd79a-Tsc1 KO kidneys at 4 weeks of age, very few apoptotic nuclei were seen in the cyst lining and interstitium." (PMID 36627370, 2023). "In Cd79a-Tsc1 KO kidneys, cilia are elongated in distal tubule cells at P9 before cysts overtly arise, suggesting that cilia length defects may contribute to cyst initiation." (PMID 36627370, 2023). "In contrast, in Cd79a-Tsc1 KO mice, pre-cystic tubule cells around P11 showed both distorted CE and OCD and cilia elongation, all of which preceded overt cyst appearance." (PMID 36627370, 2023).
X-linked agammaglobulinemia (10 papers, 2006 to 2025). X-linked agammaglobulinemia (XLA) is a clinically variable form of isolated agammaglobulinemia, an inherited immunodeficiency disorder (see this term), and is characterized in affected males by recurrent bacterial infections during infancy. "Fourth, genetic mutations of non-X linked agammaglobulinemia encoding for pre-BCR and/or BCR complex (such as IGHM, CD79a, CD79b, and IGLL1 genes) and for activating mTOR signaling (such as PI3KD and PIK3R1 genes)." (PMID 33013854, 2020).
acute lymphoblastic leukemia (9 papers, 1980 to 2024). Leukemia with an acute onset, characterized by the presence of lymphoblasts in the bone marrow and the peripheral blood. "The study of expression of the mb-1 (CD79a) chain is of significant interest in B acute lymphoblastic leukemia (B-ALL) lineage assessment." (PMID 34706776, 2021). "Since this case is potentially interesting, we report a B acute lymphoblastic leukemia case with a lack of expression CD79a associated with intrachromosomal amplification of chromosome 21 genetic abnormality." (PMID 34706776, 2021). "CD79a is one of the critical markers in the assignment of B acute lymphoblastic leukemia." (PMID 34706776, 2021). "Studies indicate an association between CD79A and central nervous system infiltration, as well as relapse in B cell precursor (BCP) acute lymphoblastic leukemia (ALL) patients." (PMID 39664749, 2024). "Unlike the prevalent expression of CD79a, CD79b is typically absent in pre-B-acute lymphoblastic leukemia (ALL), plasma cell tumors, and chronic lymphocytic leukemia (CLL) cases." (PMID 39682155, 2024).